LILRB1 (leukocyte immunoglobulin like receptor B1)
Diseases named in the same sentence as LILRB1 in open-access papers (continued):
Sharing a sentence is not in itself a finding about the gene and the disease.
tumor (continued). "In addition, immunoglobulin-like transcript 2 (also known as LILRB1) can also inhibit the proliferation and cytotoxic activity of infiltrating NK cells in GC tumor tissues, so blocking this receptor can enhance the activation and proliferation of NK cells." (PMID 36225938, 2022). "While LILRB1 and LILRB2 recognize the conserved α3 and B2M domains in most HLA haplotypes, HLA-G has emerged as an interesting binding partner due to its more restricted expression on tumor cells." (PMID 35865547, 2022). "Although MHC-I or LILRB1 blockade promotes macrophage-mediated phagocytosis, it does not extensively inhibit tumor growth in immunocompetent mice, indicating some of the limitations of this therapy." (PMID 35978372, 2022). "Since the discovery of the first tumor phagocytosis-related checkpoint, namely the CD47/SIRPα axis, in the late 2000s, other tumor phagocytosis-related checkpoints have been identified: the PD-1/PD-L1 axis, MHC-I/LILRB1 axis, and CD24/SIGLEC-10 axis." (PMID 35978372, 2022). "The anti-HLA-G scFv may compete with LILRB1 and KIR2D4 receptors on NK cells for HLA-G protein on the tumor membrane, thereby activating NK cell cytotoxicity by downregulating phosphorylated SHP-1 and upregulating phosphorylated Syk/Zap70." (PMID 34663641, 2021). "In parallel, tumor cells isolated from MCS–monocytes coculture expressed the “do not eat me” signal CD47 as well as PD-L1 and HLA molecules (HLA-A and HLA-B), which are recognized ligands for PD-1 and LILRB1, respectively." (PMID 33922336, 2021). "In this regard, LILRB1 expression is not restricted to macrophages – it is also expressed on DC, and its engagement on these cells is therefore likely to interfere with tumor uptake and immune stimulation by this innate population as well." (PMID 32508018, 2020). "Additionally, inhibitory interactions between LILRB1 on phagocyte surfaces and the β2-microglobulin subunit of MHC-I molecules on tumor cell surfaces may contribute to tumor cell resistance to phagocytosis." (PMID 40463500, 2025). "Therefore, when LILRB1 ligates MHC1, it inhibits innate immune cells mediated anti-tumor responses." (PMID 38911856, 2024). "Indeed, the murine macrophage receptor LILRB1 does not cross-react with human β2m, and PD-1 was not present on tumor-infiltrating macrophages nor on neutrophils before ACT." (PMID 38828721, 2024). "Disrupting either MHC-I or LILRB1 can facilitate phagocytosis, suggesting that the MHC-I/LILRB1 axis plays a vital role in inhibiting macrophage phagocytosis, which shows potential to be a possible marker for therapeutic response to CD47-targeted agents and target of anti-tumor therapy." (PMID 37345054, 2023). "The HLA-G molecule can interact with leukocyte receptors (e.g., ILT-2 [LILRB1/CD85j], ILT-4 [LILRB2/CD85d], and KIR2DL4 [CD158d]), mostly on CD8+ T and natural killer (NK) cells, inducing inhibitory cytotoxic responses, facilitating tumor cell proliferation and spread." (PMID 37569841, 2023). "Potential pitfalls in the clinical application of LILRB1 directed antibodies may arise from antigen sink due to LILRB1 expression by tumor cells or immune cells that may not contribute to eradication or play only minor roles." (PMID 37781391, 2023). "MHC-I expression on tumor cells renders their resistance to phagocytosis, which may be because of the inhibitory interaction between the β2M subunit of MHC-I on cancer cells and LILRB1 on phagocytes." (PMID 36882399, 2023). "In addition, in a tumor context, NK cell education may also be led by TIGIT, CD226 and SLAM, as well as LIR-1 (LILRB1) in addition to traditional KIR- and HLA-based education." (PMID 36742337, 2023). "Thus, in patients with normal or high MHCI expression in tumor cells, drugs targeting the MHCI/LILRB1 axis may facilitate antitumor immune responses and act synergistically with drugs targeting the CD47/SIRPα axis." (PMID 35892835, 2022).
tumor (continued). "Therefore, in patients with normal or high expression of MHCI on tumor cells, drugs targeting the MHCI/LILRB1 axis may promote anti-tumor immune responses and play a synergistic effect with drugs targeting CD47/ SIRPα axis." (PMID 34625124, 2021). "Interestingly, LILRB1 is mainly expressed around tumor cells rather than on tumor cells in patients with GC." (PMID 34485116, 2021). "The anti-HLA-G scFv component may compete with LILRB1 and KIR2D4, both of which are expressed by NK cells, to hijack tumor HLA-G and activate NK cell cytotoxicity by downregulating phosphor-SHP-1 and upregulating phosphor-Syk/Zap70 (thereby converting inhibitory signals to activating signals)." (PMID 34663641, 2021). "However, the effect of LILRB1 on TAMs and its role in the tumor microenvironment has not yet been analyzed systematically in GC." (PMID 34485116, 2021). "As such, the engagement of LILRB1 and LILRB2 by their high-affinity ligand HLA-G is an important immunosuppressive pathway at the fetal-maternal interface during pregnancy and may be involved in tumor immunoevasion." (PMID 32870822, 2020). "In addition to CD47, the macrophage surface leukocyte immunoglobulin-like receptor B1(LILRB1) protein can specifically recognize major histocompatibility complex I(MHC I) and microglobulin-like β2 (β2M) on the surface of tumor cells, allowing tumor cells to directly escape macrophage phagocytosis." (PMID 36911723, 2023). "Interestingly, we found that LILRB1 was mainly present in tumor stroma rather than tumor cells." (PMID 34485116, 2021). "Tumor conditioning upregulates macrophage CD163, CD206, CD80, and LILRB1 without impairing phagocytosis; CD47 blockade similarly enhances A2780 cell clearance in conditioned and control macrophages." (PMID 41280929, 2025). "LILRB1 inhibition combined with anti-CD47 monoclonal antibody treatment improved the macrophage phagocytosis and tumor-killing effects, without hurting normal cells." (PMID 35646915, 2022). "While the anti-LILRB2 antibody was not effective, the anti-LILRB1 antibody enhanced ADCP considerably, but strictly required simultaneous CD47 blockade and the presence of a tumor targeting CD20 antibody to become effective." (PMID 36389667, 2022). "Additionally, treatment with RSL3 in NSG mice did not significantly affect the tumor burden of CTR-KD ARP-1 cells; however, it inhibited MM progression in mice bearing LILRB1-KD ARP-1 cells." (PMID 38982045, 2024).
cancer (72 papers, 2013 to 2026). A tumor composed of atypical neoplastic, often pleomorphic cells that invade other tissues. "Intriguingly, the expression of LILRB1 may increase the susceptibility of cancer cells to an attack by immune cells." (PMID 37781391, 2023). "Moreover, a pan-cancer genomics analysis showed that LILRB1 was highly mutated in various cancers." (PMID 38022598, 2023). "Immunosuppressive signaling nodes between the MHC class I molecule, HLA-F, on both cancer basal cells and CAFs and the inhibitory receptor, leukocyte immunoglobulin like receptor B1 (LILRB1), on monocyte/macrophages, were also noted in older patients." (PMID 41188599, 2025). "To assess LILRB1 levels on cancer cells post-CAR treatment, we isolated spleens from the mice at the time of sacrifice." (PMID 40186066, 2025). "This review focuses on this newly emerged immune checkpoint and summarizes the current understanding of MHC1/LILRB1 axis on mediating cancer evasion from innate immune cells and the therapeutic potential to block this axis for cancer therapy." (PMID 38911856, 2024). "Immune-suppressive signaling nodes between the class I molecule, HLA-F, on both CAFs and cancer basal cells with the inhibitory receptor, leukocyte immunoglobulin like receptor B1 (LILRB1), on monocyte/macrophages were also noted in older TNBC patients." (PMID 39483921, 2024). "MHC1/LILRB1 seems to be such an axis to regulate innate immune responses for various types of cancer." (PMID 38911856, 2024). "The review aims to summarize the current understanding of MHC1/LILRB1 axis on mediating cancer immune evasion with an emphasis on the therapeutic potential to block this axis for cancer therapy." (PMID 38911856, 2024). "Novel immunotherapy strategies can be developed by effectively modulating the activity and function of macrophages like blocking MHC1/LILRB1 axis to suit different cancer types and individual patient characteristics." (PMID 38911856, 2024). "The MHC1/LILRB1 axis represents such a critical facet of the intricate interplay between cancer cells and the innate immune system, offering a unique perspective in the field of cancer immunotherapy." (PMID 38911856, 2024). "Intriguingly, therapeutic blockades disrupting MHC1/LILRB1 interaction have been advanced in clinical trials, displaying a great promise for the therapy of cancer." (PMID 38911856, 2024). "By presenting MHC-I molecules that engage LILRB1, cancer cells can inhibit the phagocytic function of immune cells, thereby evading immune surveillance." (PMID 38881902, 2024). "Targeting the MHC class I/LILRB1 interaction to enhance TAM phagocytosis is a potential therapeutic approach to cancer treatment." (PMID 38258072, 2023). "Like other members of the LIR family, LILRB1 plays a role in different diseases including pathogen infection, certain autoimmune diseases and cancer." (PMID 37781391, 2023). "More recently, HLA class I expression was demonstrated to protect cancer cells from phagocytosis by macrophages via interaction with LILRB1, rendering LILRB1 also a phagocytosis checkpoint." (PMID 37781391, 2023). "In this review, we introduce LILRB1 and highlight the features that make this immune checkpoint a promising target for cancer immunotherapy." (PMID 37781391, 2023). "The promising pre-clinical results achieved by targeting LILRB1 have paved the way for first clinical trials with individual LILRB1 antagonists in cancer patients." (PMID 37781391, 2023). "Here, the immune checkpoint LILRB1 is introduced putting a focus on its role in the regulation of monocytes, macrophages and cytotoxic lymphocytes, and perspectives for LILRB1 targeting in the treatment of cancer are outlined." (PMID 37781391, 2023). "Of note, in the peripheral blood of cancer patients an increased frequency of LILRB1 expressing NK and T cells was observed compared to healthy controls." (PMID 37781391, 2023).
cancer (continued). "Major histocompatibility (MHC) class I–LILRB1/LILRB2 signaling axis: The expression of major histocompatibility complex class I (MHC I) on cancer cells hinders phagocytosis by interacting with the leukocyte immunoglobulin-like receptor (LILRB1) on macrophages." (PMID 38258072, 2023). "Currently, the receptor is evaluated as a target pre-clinically and first clinical trials with individual LILRB1 targeted agents have been initiated to evaluate the potential of LILRB1 blockade in cancer patients." (PMID 37781391, 2023). "To explore the possible role of LILRB1, we examined the expression of the LILRB1 gene in different cancers by using data from UCSC XENA." (PMID 37142967, 2023). "LILRB1 blockade enhances anti-cancer immunity of NK cells and CD8+ T cells similar to the blockade of the PD-1/PD-L1 axis." (PMID 35784341, 2022). "Preclinical studies pointed out that LILRB1 is highly expressed by TAMs and is responsible for the resistance of cancer cells expressing the common MHC-I component β2M to anti-CD47-induced phagocytosis." (PMID 35158779, 2022). "MHC-1 expressed by cancer cells binds with leukocyte immunoglobulins (LILRB1) on TAMs and inhibits phagocytosis, which leads to deprivation of immune surveillance; interestingly, disruption of MHC-1 or LILRB1 enhances the phagocytosis of cancer cells." (PMID 35183252, 2022). "Upregulation of either LILRB1 or LILRB2 in macrophages has shown an evasion mechanism for cancer cells against phagocytosis." (PMID 32292502, 2020). "The role of HLA-G (through the interaction with LILRB1) in the control of antitumor immune response has also been confirmed both in cancer patients and in murine models of human tumors." (PMID 27652273, 2016). "Notably, it is reported that the ratio of LILRB1 expressing NK cells is higher in the peripheral blood of cancer patients compared to healthy controls." (PMID 38911856, 2024). "Importantly, we validated in this study the inhibitory activity of a newly identified anti-LILRB1 antibody, which opens up perspectives for its use in cancer therapies." (PMID 39237366, 2024). "Given the fact that TB patients are often complicated by concurrent cancer or co-infections, targeting LILRB1 could be a multi-pronged strategy that meets the needs of TB patients with those comorbidities." (PMID 39030302, 2024). "Correspondingly, disrupting MHC1/LILRB1 has shown both preclinical and clinical therapeutic activity against several types of cancers, behaving like the established immune checkpoints such as PD-1/PD-L1 and CD47/Sirpα which have been extensively reviewed elsewhere." (PMID 38911856, 2024). "LILRB1 has gained increasing attention as it has been demonstrated to function as a phagocytosis checkpoint on macrophages by recognizing HLA class I, which represents a ‘Don’t Eat Me!’ signal that impairs phagocytic uptake of cancer cells, similar to CD47." (PMID 37781391, 2023). "There is strong evidence that LILRB1 mediates cancer immune-evasion." (PMID 38022598, 2023). "Potential mechanisms for the recognition of HLA-class-I-negative phenotypes may include KIR-, NKG2A- and LILRB1-mediated interactions with target cancer cells." (PMID 36631610, 2023). "Furthermore, HLA-F was upregulated in cancer cells from the S components, which was shown to be correlated with the upregulation of LILRB1/LILRB2 in macrophages." (PMID 35874770, 2022). "Further, LILRB1 is known to contribute to the immune evasion of various cancers." (PMID 35784341, 2022). "This seems to be the case for LILRB1 gene variants, which are absent in the world’s cancer datasets but were present in high frequencies among these GC patients and Amerindians." (PMID 36551612, 2022). "Furthermore, blocking LILRB1 increased both natural cytotoxicity as well as cetuximab-mediated ADCC, especially when both NK cells and cancer cells expressed LILRB1." (PMID 34557197, 2021).
cancer (continued). "In addition, Mo-TAMs expressed SIRPA and showed a selective upregulation of PD1 and leukocyte immunoglobulin-like receptor LILRB1, two additional inhibitory receptors impairing macrophage-dependent clearance of cancer cells." (PMID 33922336, 2021). "Noteworthily, the expression of SIRPα, SIGLEC10, and LILRB1 also increased in cancer tissues." (PMID 34778091, 2021). "However, given that different breast and colorectal patient cancers upregulate the LILRB1 ligand HLA-G as a means of evading NK targeting and killing, LILRB1 is likely to be important in tumor immunity." (PMID 32290478, 2020). "The LILRB1 gene variants, absent in the world’s cancer datasets but present in high frequencies among the studied GC patients, may represent essential cancer variants specific to the Amerindian ancestry’s contributions." (PMID 36551612, 2022). "Finally, LILRB1 silencing rescued NK cell antitumor activity in a xenograft cancer model." (PMID 27652273, 2016). "The immunomodulatory roles of LILRB1 and LILRB2 receptors make them promising targets for therapies in various types of cancer." (PMID 41583460, 2025). "HLA-G and its receptors are considered as a new immune checkpoint and potential targets for cancer immunotherapy, and several antibodies targeting HLA-G, LILRB1, or LILRB2 are currently in clinical trials for cancer treatment." (PMID 39237366, 2024). "HLA-B57:01:01 has a similar profile as HLA-B27 by binding to LILRB1, LILRB2 and KIR3DL1 receptors, both LILRB1 and LILRB2 checkpoint receptors are of wide clinical interest in cancer immunotherapy." (PMID 39199672, 2024). "Phagocytosis checkpoints, including PDCD1, LILRB1, SIGLEC10, and SIRPα are significantly for the function of TAMs in many cancers." (PMID 35317832, 2022). "Disruption of MHC-I or LILRB1 potentiated the macrophages' phagocytosis of cancer cells, which defined the MHCI-LILRB1 pathway axis as an “eat me/don't eat me” signal." (PMID 35585567, 2022). "Another important immune checkpoint is represented by leukocyte immunoglobulin-like receptor B1 (LILRB1), which suppresses TAM phagocytic functions through the engagement of the MHC class I component β2-microglobulin (β2M) on cancer cells." (PMID 32456204, 2020). "They found that leukocyte immunoglobulin-like receptor B1 (LILRB1) on the surface of TAMs binds to a portion of MHC-I on cancer cells, which inhibited the ability of macrophages to engulf the cancer cells." (PMID 30062558, 2018). "MHC1 appears to be such a molecule expressed on cancer cells which can transmit a negative signal to innate immune cells through interaction with leukocyte immunoglobulin like receptor B1 (LILRB1)." (PMID 38911856, 2024). "Moreover, blocking inhibitory receptors on NK cells, such as LILRB1, KIR and NKG2A, with specific antibodies has been demonstrated to enhance NK cell function against cancer cells." (PMID 38911856, 2024). "More recently, LILRB1 blockade was shown to enhance cytotoxic CD8+ T cell activity using bispecific T cell engager (BiTE) molecules, highlighting the potential of the LILRB1 receptor as an anti-cancer therapeutic target." (PMID 32373555, 2020). "In addition, several other anti-phagocytic surface proteins (immune checkpoint) such as PDL1, LILRB1, B2M, and CD24 have also been found to inhibit the phagocytosis of cancer cells both in the in vitro co-culture of cancer cells with macrophages as well as in vivo." (PMID 36679900, 2022). "In addition, we found that Mo-TAMs heightened the expression of LILRB1, a hitherto uncharacterized inhibitory receptor in the context of MPM disease, that recognizes MHC class I complexes and impairs the ability of TAMs to clear different types of cancer cells both in vitro and in vivo." (PMID 33922336, 2021). "LILRB1 and LILRB2 expressed in macrophage subsets were found to interact with the nonclassical human leukocyte antigen HLA-F expressed in cancer cells." (PMID 39669575, 2024).
infection (15 papers, 2008 to 2025). The state of being infected such as from the introduction of a foreign agent such as serum, vaccine, antigenic substance or organism. "In TB granulomas, LILRB1 expression is upregulated on NK cells, implying compromised NK cell functions in the Mtb-infection microenvironments." (PMID 39030302, 2024). "Without expressing proteins that specifically modify phagosome acidification, DENV indirectly alters the phagosome environment by co-ligation of LILRB1 during antibody-dependent infection." (PMID 28084461, 2017). "Our data show that Pf-infection induced an increased frequency of δγ T cells expressing LILRB1." (PMID 35911674, 2022). "Likewise, blocking LILRB1 with anti-LILRB1 antibodies in primary monocytes increased phagosome acidification during ADE infection." (PMID 28084461, 2017). "Similarly, to monocyte subsets, LILRB1+δγ T cells could also be inhibited by RIFINs or MHC-I ligands during infection leading to decreased IFN-γ production and cytotoxic activity." (PMID 35911674, 2022). "Moreover, levels of LILRB1 and LILRB2 expression were higher during symptomatic attacks than during asymptomatic infections." (PMID 35911674, 2022). "Indeed, given their strong capacity to attenuate immune response, LILRB1 and LILRB2 represent potential targets for pathogens to evade immune recognition, thereby extending the duration of infection." (PMID 35911674, 2022). "Notably, the inhibitory receptors LILRB1 and LILRB2, which restrain antigen presentation and inflammatory signaling, were upregulated in response to HCMV, with LILRB2 being more prominently induced following TB40 infection." (PMID 40980889, 2025).